GDA (guanine deaminase)
Description:
Catalyzes the hydrolytic deamination of guanine, producing xanthine and ammonia.
Synonyms: Guanase; GAH; CYPIN; NEDASIN
Tractability: Small molecule: a structure with a bound ligand is known; it has a high-quality binding pocket. PROTAC: ubiquitination databases record sites on it; its protein half-life has been measured; a small molecule that binds it is known.
Target class: Enzyme; Hydrolase
Gene: Protein-coding gene on chromosome 9 (72,114,595 to 72,257,193, forward strand). Ensembl gene ENSG00000119125.
Subcellular location (Human Protein Atlas): Nucleoplasm
Pathways (Reactome):
Metabolism: Purine catabolism
Gene Ontology:
Molecular function: guanine deaminase activity; protein binding; zinc ion binding; hydrolase activity; hydrolase activity, acting on carbon-nitrogen (but not peptide) bonds
Biological process: guanine catabolic process; nervous system development; nucleobase-containing compound metabolic process; deoxyguanosine catabolic process; dGMP catabolic process; GMP catabolic process
Cellular component: cytosol
Genetic constraint (gnomAD): Loss-of-function variants: 1 observed, 3.97 expected, observed/expected ratio (o/e) 0.25, 90% interval 0.088 to 1.18. That is too few expected variants to judge how well the gene tolerates losing a copy. Missense variants: 50 observed, 63.41 expected, observed/expected ratio (o/e) 0.79, 90% interval 0.63 to 1. Synonymous variants: 34 observed, 27.49 expected, observed/expected ratio (o/e) 1.24, 90% interval 0.94 to 1.64.
Homologues: Orthologues: chimpanzee GDA (99% identical), macaque GDA (96% identical), rabbit GDA (93% identical), mouse Gda (91% identical), pig GDA (91% identical), rat Gda (91% identical), guinea pig GDA (86% identical), dog GDA (83% identical), tropical clawed frog gda (59% identical), zebrafish gda (58% identical), Drosophila melanogaster DhpD (43% identical), Caenorhabditis elegans cpin-1 (9% identical).
Diseases named in the same sentence as GDA in open-access papers:
GDA is named in the same sentence as 21 diseases in open-access papers, as found by Europe PMC text mining. Sharing a sentence is not in itself a finding about the gene and the disease. The quoted sentences say what the papers report.
melasma (4 papers, 2020 to 2023). "In fact, GDA upregulation has been reported in melasma, a representative pigmentary skin disorder, in addition to seborrheic keratosis." (PMID 34830382, 2021). "In our previous study using DNA microarray from melasma lesions, GDA was shown to be one of the most upregulated genes, which was validated by qRT-PCR analysis." (PMID 32517074, 2020). "Our previous study used microarray to show that guanine deaminase (GDA) gene expression is highly increased in melasma lesions." (PMID 32517074, 2020). "Melasma is a hyperpigmentation disorder caused by UV irradiation and inflammation, and the expression of GDA mRNA is 5~14-fold higher in melasma lesions than in non-lesioned tissues." (PMID 38066959, 2023). "In our previous study, we found that guanine deaminase (GDA) mRNA expression was 5 to 14-fold higher in melasma lesion tissue than in non-lesion tissue." (PMID 32517074, 2020).
lung carcinoma (2 papers, 2022 to 2025). "The “new” autoantibodies in our panel target TAAs like DCTPP1, GIMAP4, WWP2, MGMT, KCMF1, and GDA, which have demonstrated links to lung cancer pathogenesis." (PMID 39661479, 2025).
seborrheic keratosis (2 papers, 2021 to 2023). A common benign skin neoplasm usually affecting older individuals. "Uric acid generated by upregulated guanine deaminase (GDA) has been identified to cause UV-induced keratinocyte senescence in seborrheic keratosis." (PMID 34830382, 2021). "In seborrheic keratosis, guanine deaminase upregulation increased UV-induced keratinocyte senescence, via uric acid formation mediated by reactive oxygen species followed by DNA damage." (PMID 38066959, 2023). "Overall, GDA upregulation in seborrheic keratosis plays a role in melanogenesis via its metabolic end product uric acid, suggesting that seborrheic keratosis as an example of hyperpigmentation associated with photoaging." (PMID 34830382, 2021).
café au lait macules (1 paper, 2020). "RNA microarray analysis showed that GDA expression level was increased in RM lesions, but its expression in sporadically-occurring congenital hyperpigmentary lesions of café au lait macules was lower than that in perilesions in our preliminary study (data not shown)." (PMID 32517074, 2020).
chordoma (1 paper, 2025). Chordomas are rare malignant tumors arising from embryonic remnants of the notochord in axial skeleton. "The expression analysis identified significant downregulation of SPOCK3, NRK, MYH8, DLK1 and SLN, alongside upregulation of HLA-DQA1, GDA, CXCL11, CXCL9 and ADAMDEC1 in chordomas." (PMID 40386066, 2025).
chronic hepatitis (1 paper, 2014). An active inflammatory process affecting the liver for more than six months. "Xanthines are catabolized from guanine by guanine deaminases (GDA), and higher levels of GDA activity were associated with liver diseases, like chronic hepatitis, biliary obstruction, and liver cirrhosis." (PMID 25265166, 2014).
glioblastoma (1 paper, 2024). The most malignant astrocytic tumor (WHO grade IV). "In contrast, elastin microfibril interfacer 2 (Emilin2), guanine deaminase (GDA), haptoglobin (Hp) and selectin L (Sell) were enriched in macrophages/monocytes in RCAS and GL261 mouse models of glioblastoma." (PMID 38712663, 2024).
gout (1 paper, 2022). A condition characterized by painful swelling of the joints, which is caused by deposition of urate crystals. "Uric acid, which causes gout, is the end product of purine catabolism, synthesized by xanthine oxidase, guanine deaminase, adenine deaminase, purine nucleoside phosphorylase, and 5-nucleotidase II." (PMID 36013310, 2022).
oral cancer (1 paper, 2020). "The overexpression of GDA in invasive oral cancer results in accelerating DNA turnover." (PMID 32672400, 2020).
cancer (1 paper, 2025). A tumor composed of atypical neoplastic, often pleomorphic cells that invade other tissues. "KCMF1 and GDA, not previously reported in LUAD, have emerged as potential cancer biomarkers." (PMID 39661479, 2025).
GDA also shares sentences with these, for which no sentence is quoted: skin (2 papers); autism (1); autism spectrum disorder (1); bone disorder (1); cervical carcinoma (1); cervical intraepithelial neoplasms (1); endothelial dysfunction (1); eye disorder (1); liver diseases (1); lung adenocarcinoma (1); neurodevelopmental disorder (1).